AKT1 (AKT serine/threonine kinase 1)
Diseases named in the same sentence as AKT1 in open-access papers (continued):
Sharing a sentence is not in itself a finding about the gene and the disease.
breast cancer (continued). "Additionally, phosphorylation of AKT at Ser473 can promote breast cancer metastasis, and increased AKT1 activity has been observed in 40% of breast cancers." (PMID 37596643, 2023). "In many cases, breast cancer metastasis may be under the control of balance between Akt1 and Akt2 and their link with MiR-200/Zeb/E-cadherin axis." (PMID 38002001, 2023). "Additionally, activating mutations in other genes in the PI3K signaling pathway, such as AKT1, are also commonly found in breast cancer." (PMID 37109059, 2023). "Additionally, TPI1 promotes the progression of breast cancer cells by regulating cell division cycle proteins and activating phosphoinositide 3-kinase/AKT serine/threonine kinase 1/mammalian target of rapamycin pathway." (PMID 38102653, 2023). "Moreover, an analysis of hotspot mutations in the genes PIK3CA, ESR1, AKT1 and ERBB2 frequently present in breast cancer was performed." (PMID 36823365, 2023). "Additionally, the tumor inhibitory function of miR-215 was found to target NOB1 in ovarian cancer and by targeting AKT serine/threonine kinase 1in breast cancer." (PMID 36759799, 2023). "Breast cancer patients were more likely to have the frequencies of AKT-1 (rs1130233 G > A genotypes GG (50%), GA (40%), and AA (10%), compared to gender matched controls who were more likely to have frequencies of GG (78.43%), GA (19.60%), and AA (1.90%), respectively." (PMID 36831624, 2023). "In agreement with our findings, other authors reported that high levels of the AKT1 isoform could be related with the loss of BRCA1 expression and HR inhibition in breast cancer models, suggesting that a similar mechanism could be possible in HGSOC." (PMID 35053468, 2022). "This suggests that biological effects of generally noticed AKT1-hyperactivation in human cancers, including breast cancer, might be impacted by co-overexpression of AKT1 status-dependent expression of a subset of genes." (PMID 35892586, 2022). "High vs. normal BMI is associated with higher levels of gene expression for AKT-mTOR pathway genes in breast cancer, but in our analysis, the association of race and AKT1 expression did not change after adjusting for BMI." (PMID 35608730, 2022). "These authors showed that mutating AKT1-Arg 15 to lysine failed to impact AKT1 SDMA in breast cancer lines, which contrasts with our findings in neuroblastoma." (PMID 35803962, 2022). "Another potential mechanism by which Akt1 inhibits breast cancer migration may act through the inhibitory role of Akt1 on ERK activation." (PMID 36180910, 2022). "However, at the same time, active AKT1 is necessary for mammary tumor development driven by ErbB2 or PyMT, since its ablation in double transgenic mice interferes with tumor growth." (PMID 35681625, 2022). "Whole-exome sequencing by The Cancer Genome Atlas (TCGA) program has confirmed earlier work, showing that gain of function mutations in PIK3CA and AKT1, and inactivating mutations in PTEN are common in ER+ breast cancer (32–49%, 13–24%, and approximately 7% respectively)." (PMID 36046843, 2022). "In addition, AKT1 was recently indicated to degrade phosphorylation-dependent Twist1, and subsequently inhibited epithelial-to-mesenchymal transition in breast cancer." (PMID 35013126, 2022). "Ablation of AKT1 or AKT2 in murine breast cancer models and of AKT1 or AKT2 in human breast cell lines was associated with suppression of tumor progression and cell-cycle progression, increased apoptosis, and an overall reduced metastatic potential of target cells." (PMID 35892586, 2022).
breast cancer (continued). "Since the initial observation that S326 phosphorylation affects heat stress‐induced HSF1 activity, five kinases have been observed to phosphorylate S326, including mTORC1, MEK1, p38, DYRK2 and AKT1, which our work previously identified can phosphorylate S326 in breast cancer." (PMID 35080342, 2022). "A broader significance of this finding might be that 25 of such loss-of-AKT1-associated upregulated genes, implying that these might be normally inhibited by AKT1, have been shown to be downregulated in breast cancer." (PMID 35892586, 2022). "We next examined the expression of AKT1, 2, and 3 in Breast Cancer METABRIC TCGA datasets." (PMID 35892586, 2022). "We observed that silencing of the endogenous AKT1 and/or inhibiting AKTs could alter the expression of up- and downregulated differentially expressed transcripts in breast cancer cells." (PMID 35892586, 2022). "Silencing of Vav1 resulted in the increased expression in Akt1 in ER+ cells and in the up-modulation of Akt2 in ER- breast tumor cells, including those with a triple negative phenotype, still representing the most aggressive breast cancer." (PMID 35743776, 2022). "Moreover, a basket trial of capivasertib treatment of patients with AKT1 (E17K)-mutated tumors demonstrated an objective response rate of 33%, with clinical benefit in ER+/HER2− breast cancer." (PMID 36010585, 2022). "In contrast, Akt1 is shown to reduce cell migration and invasion in breast cancer cells." (PMID 36180910, 2022). "Interestingly, EGF stimulation of breast cancer cells leads to 945 splice variances in cells with AKT1 knockdown and 442 splice variances in Inhibitor VIII-treated cells." (PMID 35892586, 2022). "However, Akt1 inhibits breast cancer migration and metastasis, while Akt2 exhibits an opposite phenomena." (PMID 36180910, 2022). "In contrast, the expression of AKT2 somewhat overlapped with that of AKT1, suggesting that resulting phenotypes in mammary epithelial cells and, perhaps, in breast cancer, could be differentially affected by AKTs." (PMID 35892586, 2022). "AKT mutations rarely occur, but amplification and overexpression of AKT gene (the most common one is AKT1) can be found in various cancers, including gastric cancer, breast cancer, colon cancer, esophageal cancer, ovarian cancer, pancreatic cancer, thyroid cancer, and glioblastoma." (PMID 35422862, 2022). "In brief, we observed that AKT1 could regulate specific set of genes and thus could influence the nature of breast cancer transcriptome." (PMID 35892586, 2022). "We could find the aberrant expression of AKT1 in many cancers including gastric, pancreatic, ovarian, lung, and breast carcinoma." (PMID 35612641, 2022). "It remains to be seen whether selective Akt1 inhibitors will be developed in the near future to treat breast cancer metastasis." (PMID 35578699, 2021). "However, recently published results from the AACR Project GENIE, which incorporated a large group of estrogen receptor positive breast cancer patients, reported that AKT1 mutant cases had comparable survival rates compared to AKT1 wild-type controls." (PMID 34670536, 2021). "WDR26, a WD40 protein that is overexpressed in highly malignant breast cancers and is associated with poor survival of breast cancer patients, selectively bound to Akt2 and not Akt1." (PMID 34298660, 2021). "It was stated that the average expression level of the PIK3CA, PIK3R1, PTEN genes in the group of breast cancer patients is lower in comparison to the control group, while the average expression level of the AKT1 and mTOR genes in the studied group was higher in comparison to the control group." (PMID 33669698, 2021). "Similarly, activating mutations in AKT1 occur in nearly 4% of Luminal, and genetic amplifications of AKT2 and PDK1 are observed in all breast cancer subtypes with a frequency of 3% and 20–38%, respectively." (PMID 34298731, 2021). "Few studies have described the tumor suppressor role of AKT1 in breast cancer." (PMID 33498407, 2021).
breast cancer (continued). "In order to extend the knowledge, we assessed the prevalence of the E542K, E545K, H1047R mutations within the PIK3CA gene and the E17K mutation within the AKT1 gene, and the expression of the PIK3CA, PIK3R1, PTEN, AKT1, mTOR genes in a cohort of patients with breast cancer." (PMID 33669698, 2021). "For example, constitutively-active Akt1 in transgenic mouse mammary glands mediates lipid accumulation during pregnancy, but mostly general Akt studies have made the connection between Akt and lipid metabolism in breast cancer." (PMID 34298660, 2021). "THSWD treatment of breast cancer may be related to targeting Ras, FoxO, PI3K-Akt, and other signal pathways associated with the core targets HRAS, MAPK1, AKT1, GRB2, and MAPK14." (PMID 34513708, 2021). "CXCR2-mediated breast cancer metastasis corelated with lower AKT1 expression." (PMID 33498407, 2021). "Knockdown of Akt1 and Akt3 in ErbB2-positive Erα-negative mouse mammary tumor C4 cells caused a substantial decrease in cell proliferation whereas Akt2 knockdown had only a modest effect." (PMID 34298660, 2021). "Four genes (AKT1, ERBB2, KMT2C, and USP34) were associated with survival of breast cancer." (PMID 34408553, 2021). "Furthermore, we also confirmed the previously reported pro-proliferative role of AKT1 for breast cancer cells in the 231-BO cell line." (PMID 33670586, 2021). "This relationship shows Akt1′s involvement in a critical regulatory step that blocks glucose from leaving the cell due to conformational changes from hexokinase phosphorylation resulting in increased glycolysis by breast cancer cells." (PMID 34298660, 2021). "After prognosis analysis, we found four genes (AKT1 (AKT serine/threonine kinase 1), ERBB2 (Erb-B2 receptor tyrosine kinase 2), KMT2C (lysine methyltransferase 2C), and USP34 (ubiquitin specific peptidase 34)) associated with survival of breast cancer." (PMID 34408553, 2021). "While Akt1 still inhibits breast cancer cell migration, Akt2 promotes breast cancer cell migration." (PMID 34419139, 2021). "Additionally, we identified a significant association of genes involved in treatment response in breast cancer with genes producing splicing-derived neoepitopes (ERBB2, ESR1, TIMP1, ABCC3) or potentially depleted self-epitopes (AKT1, CCNE1, RET, TFF3)." (PMID 34529669, 2021). "Similarly, AKT1 and PIK3CA mutations harbored relatively higher VAFs in our Chinese breast cancer cohort." (PMID 33173047, 2020). "However, when grouping samples with both AKT1-E17K and NF1 mutations, breast cancer becomes the most prevalent, corresponding to 73% of all tumors." (PMID 32858845, 2020). "Thus, we believe our data support a general effect of EDNRB-442 on breast cancer cell invasion and AKT1 activation across subtypes." (PMID 32201539, 2020). "Akt1 gene amplification was found in breast, colon, pancreatic, gastric, esophageal, ovarian, and thyroid cancers, and glioblastoma while amplification of Akt2 occurred in pancreatic, ovarian, and breast cancers." (PMID 32106627, 2020). "In breast cancer, the PI3K/AKT pathway is activated through PIK3CA or AKT1 mutations and PTEN loss." (PMID 33375317, 2020). "However, in oncogene-driven murine breast cancer models, constitutively active AKT1 enhanced primary tumour initiation and growth, but paradoxically inhibited metastasis." (PMID 33276499, 2020). "A few of top 20 pathways including vantveer breast cancer poor prognosis, Xu hgf signature not via AKT1 48HR and vantveer breast cancer metastasis were markedly more activated in the high‐risk patients than that in low‐risk patients." (PMID 32530136, 2020).
breast cancer (continued). "Rather, the AKT1-dependent effects of PIPP on breast cancer cell migration may relate to the relative expression or intracellular localisation of the various AKT isoforms in mammary tumours and breast cancer cell lines." (PMID 33276499, 2020). "However, invasive melanoma cells were associated with AKT1 signaling related to the migration pathway, squamous cells with the EGFR signaling in response to extracellular cues and breast cancer cells with IL-6 signaling involved in the inflammatory response." (PMID 33142759, 2020). "Several studies have shown that AKT1 leads to mammary tumor growth." (PMID 33227065, 2020). "Thus, our observations that EDNRB-442 activates pAKT1 and abrogates breast cancer invasion are consistent with previous studies describing AKT1 as a negative regulator of breast cancer." (PMID 32201539, 2020). "In addition to the abundance of publications describing an anti-migratory and anti-invasive role of AKT1, there are also indications that AKT1 has a beneficial effect on the invasion and metastasis of breast cancer." (PMID 33291460, 2020). "The isoform-specific effects can differ in the distinct stages of the breast cancer disease, e.g. AKT1 could promote tumor initiation and growth of the primary tumor, whereas AKT2 preferably promotes tumor progression and metastasis." (PMID 31752925, 2019). "However, recent data suggests that one of the mechanisms inducing chemoresistance and progression in breast cancer is driven by chemokine receptor CXCR2 overexpression, causing Akt1 suppression and COX2 activation." (PMID 31921382, 2019). "Investigations of ER positive human breast cancer probes revealed AKT1 deletions in 4.8%, AKT1 amplifications in 1%, AKT2 deletions in 21.1%, interestingly no AKT2 amplifications, no deletions of AKT3, but AKT3 amplifications in 9.9% of investigated ER-positive human breast cancers." (PMID 31752925, 2019). "The PI3K/AKT pathway is activated through PIK3CA or AKT1 mutations and PTEN loss in breast cancer." (PMID 31277699, 2019). "In addition to its separation activity the HSP70 inhibitor JG-98 was found to destabilize its “client proteins” Akt1 and Raf1 in breast cancer cells MDA-MB-231 and MCF-7." (PMID 31652993, 2019). "Moreover, the mouse mammary tumors of AKT1 knockdown cells exhibit a more spindle-shaped morphology, indicating a higher invasiveness." (PMID 31752925, 2019). "The frequency of AKT1 expression of breast cancer in general amounts to about 24%." (PMID 31752925, 2019). "According to data from the TCGA AKT1 mutations emerge in about 2.4% of breast cancer, most of them in the luminal A subtype and none of them in basal like breast cancer." (PMID 31752925, 2019). "Thus, this work provides a proof-of-concept for directly targeting BCSCs against breast cancer through inhibition of the TRIB3/AKT1 interaction." (PMID 31844113, 2019). "Moreover, the promotion of metastasis by AKT1 knockdown is mediated in a similar way compared to breast cancer." (PMID 31752925, 2019). "The opposing effect of AKT1 on metastasis between ovarian cancer and breast cancer may be due to the different ways of metastasis: breast cancer metastases are vascular metastases, whereas ovarian cancer cells metastasize directly to the peritoneal cavity." (PMID 31752925, 2019). "Akt1 was shown to stimulate the growth of breast carcinoma but inhibit its metastasis." (PMID 30956761, 2019). "Hence, we further detected the expression of β-catenin nuclear protein in breast cancer cells after Akt1 knockdown." (PMID 30445978, 2018). "However, AKT1 phosphorylation levels were significantly higher in breast cancer than in ovarian cancer lines." (PMID 30012111, 2018).
breast cancer (continued). "However, AKT1 activity has also been recently shown to repress the invasive properties of breast cancer cells in specific contexts." (PMID 29506489, 2018). "In addition, the expression of β-catenin total protein was upregulated when Akt1 was knocked down in these breast cancer cells." (PMID 30445978, 2018). "Indeed, in Akt1 impaired breast cancer cells, we also documented EGFR mediates β-catenin nuclear accumulation." (PMID 30445978, 2018). "Knockdown of Akt1 induced sustained activation of EGFR in breast cancer cells." (PMID 30445978, 2018). "Knockdown of Akt1 promotes Epithelial-to-Mesenchymal Transition in breast cancer cells." (PMID 30445978, 2018). "However, the mechanism and downstream signals by which Akt1 inhibition regulates each step of breast cancer metastasis are not completely understood." (PMID 30445978, 2018). "Obviously, Akt1 inhibition induced β-catenin nuclear accumulation was not caused by Wnt pathway activation in breast cancer cells." (PMID 30445978, 2018). "Then, we wonder whether the increased in EGFR total protein expression in Akt1 impaired breast cancer cells was dependent on its transcriptional regulation." (PMID 30445978, 2018). "To test the hypothesis, we first examined whether Akt1 inhibition could induce EGFR activation in breast cancer cells." (PMID 30445978, 2018). "In addition, an increase in EGFR total protein expression was also observed in these Akt1 knockdown breast cancer cells." (PMID 30445978, 2018). "In addition, over-expressed pAKT1 in HER2 positive breast cancer was associated with poor prognosis, indicating a post-translational modification mechanism for AKT1 in breast cancer." (PMID 28301567, 2017). "Furthermore, the short-term and long-term changes in PTEN and AKT1 gene expression subsequent to anthracycline exposure were assessed in patients with locally advanced breast cancers." (PMID 28476032, 2017). "Expression of both PIPP and AKT1 was reduced in a subset of human breast cancers and it is interesting to speculate that hyperactivated AKT2 in these tumours may promote metastasis leading to a poorer outcome although this has yet to be shown." (PMID 28082369, 2017). "We also identified 11 variants on genes known to predispose to other cancer types or cancer syndromes, like RET and AKT1, which have never been previously associated with breast cancer predisposition." (PMID 28569218, 2017). "Transgenic overexpression of constitutively active AKT1 and AKT2 in oncogene-driven mouse models of breast cancer have revealed their opposing effects on cell migration and tumour metastasis, whereby AKT1 inhibits but AKT2 promotes the establishment of metastatic lesions." (PMID 28082369, 2017). "Thus, mice with mammary gland-specific AKT1 expression that are systemically treated with the carcinogen DMBA develop breast cancer." (PMID 28903409, 2017). "However, it was obvious that the basal-like breast cancer subgroup showed the lowest mean expression level of AKT1." (PMID 28301567, 2017). "In vitro studies in breast cancer cell lines suggest that AKT1-mediated degradation of the pro-invasion transcription factor NFAT and the tumour-suppressor tuberous sclerosis complex 2 (TSC2) decreases, whereas AKT2-mediated up-regulation of pro-invasive β1-integrin promotes cell migration." (PMID 28082369, 2017).